KRAS (KRas proto-oncogene, GTPase)
Diseases named in the same sentence as KRAS in open-access papers (continued):
Sharing a sentence is not in itself a finding about the gene and the disease.
cancer (continued). "Mutation in the KRAS oncogene is one of the most frequent events in human cancers." (PMID 29721157, 2018). "Taken together, these phenotypic differences could be a contributing factor to the predominance of KRAS mutations in cancers from endodermally derived tissues such as pancreas, lung and colon." (PMID 30287508, 2018). "A mutated KRAS protein is frequently observed in human cancers." (PMID 30199525, 2018). "We hypothesize that DMF may have a preferential antitumor activity in cancers exhibiting a KRAS mutation." (PMID 29507676, 2018). "HRAS and KRAS are among the most frequently mutated genes in human cancers." (PMID 30532261, 2018). "KRAS is found to be mutated in a number of human cancers, such as CRC, pancreatic and lung cancer." (PMID 27965461, 2017). "Splicing of KRas into KRas4A and KRas4B isoforms is of interest since both isoforms will harbour the oncogenic mutations observed in ~20% of human cancers and have differential cancer promoting activities." (PMID 28117393, 2017). "Additionally, the ethnicity didn`t influence the prognostic value of KRAS mutation detected by cfDNA in cancer patients." (PMID 28796802, 2017). "Somatic mutations in the KRAS oncogene are common in human cancers." (PMID 28532404, 2017). "KRAS mutations, identified in approximately 30% of human cancers, may be associated with resistance to PI3K/AKT/mTOR inhibitors." (PMID 28945763, 2017). "However, only a subgroup of individuals with KRAS wildtype cancer benefit from C225 treatment, suggesting the existence of other drug resistance mechanisms, in addition to KRAS gene mutation." (PMID 29160412, 2017). "While only decitabine sensitivity has been linked to KRAS status so far, there is increasing evidence that both azacytidine and decitabine induce reactive oxygen species which cause DNA damage and finally apoptosis in cancer cells." (PMID 29180611, 2017). "However, the prognostic value of KRAS mutation in cell-free DNA (cfDNA) in cancer patients was conflicting." (PMID 28796802, 2017). "Similarly, two other studies were able to detect KRAS mutations in the sputum of 12.5% normal individuals compared to the 48% detection rate in cancer patients." (PMID 28199989, 2017). "However, the mutations of EGFR-downstream proteins, such as KRAS in A549, result in drug resistance, protecting cancer cells from therapeutic treatments." (PMID 28787001, 2017).
cancer (continued). "Also, while most early studies utilized the activated form of HRAS (generally referred to as RAS), each RAS isoform (HRAS, KRAS and NRAS) has a distinct biological function, and KRAS mutations are much more common in human cancers than NRAS and HRAS mutations." (PMID 28152508, 2017). "However, previous series have shown that CRC cells harboring KRAS mutations have a higher lung tropism than wild type or cancer cells harboring BRAF mutations." (PMID 27911859, 2017). "Thus, the most common methods used for KRAS mutation testing have very different LODs with possible implications for cancer treatment in tested patients." (PMID 28636636, 2017). "The remarkable prevalence of PIK3CA and KRAS mutations in DNA from normal tissues suggests that there may be significant opportunities for cancer prevention." (PMID 28755461, 2017). "The modification introduced in the ddPCR protocol facilitated the quantification of low‐copy alleles carrying driver mutations, such as oncogenic KRAS, in localized and early‐stage cancers using small blood volumes, thus offering a minimally invasive modality for timely diagnosis." (PMID 28691390, 2017). "In addition to the novel cancer genome-phenotype association, we further show here that mutant KRAS-driven MPE is mediated via CCL2-dependent paracrine signalling to CD11b+Gr1+ myeloid cells." (PMID 28508873, 2017). "In addition, the ethnicity didn’t influence the prognostic value of KRAS mutation in cfDNA in cancer patients (p = 0.39)." (PMID 28796802, 2017). "Thus, in the present study, we conducted a meta-analysis to investigate the effect of KRAS mutation detected by cfDNA on survival in patients with cancer." (PMID 28796802, 2017). "Because of the correlation of SYK mRNA expression with MSI and a previous study which showed that SYK is differentially expressed in KRAS-dependent and KRAS-independent cancer cell lines, we explored the association between known CRC mutations and SYK expression in our MATCH cohort and TCGA." (PMID 28957395, 2017). "Briefly, KRAS mutation in cfDNA was a survival prognostic biomarker in cancer patients." (PMID 28796802, 2017). "Furthermore, in vitro experiments revealed that cancer cells with KRAS codon 13 mutation had a weaker level of resistance to apoptosis than those with KRAS codon 12 mutations." (PMID 27878354, 2017). "However, their stage II carcinoma located in the rectum presented KRAS G12V and PIK3CA H1047R, two different mutations." (PMID 29069792, 2017). "Importantly, we report for the first time a significant correlation exists between the degree of interindividual variability in PIK3CA and KRAS MFs in normal tissues and the tissue‐specific prevalence of the mutations in carcinomas." (PMID 28755461, 2017). "Additionally, a very recent study assayed a panel of 47 different cancer cell lines comprised of both KRAS mutant and KRAS wild-type lines and found that the KRAS-mutated cells were no more dependent on autophagy than their wild-type counterparts." (PMID 27096871, 2016). "We reasoned that genetic alterations in these cancer cell lines other than mutations in KRAS might affect their response to anti-mitotics." (PMID 27412232, 2016). "Second, while “in vitro artifacts” would be irrelevant to natural selection processes, the observed prevalence of detected mutations in common cancer hotspots (e.g., position G12 in KRAS) is more suggestive of an oncogenic selection process resulting in a typical cancer gene mutation distribution." (PMID 28027320, 2016).
cancer (continued). "Terpinen-4-ol restores the activity of cetuximab in cancers with mutated KRAS." (PMID 27275783, 2016). "The KRAS G12V mutation is known as a driver mutation of MMs as well as other cancers." (PMID 27223072, 2016). "Left-side cancers were more common in KRAS mutation female patients." (PMID 26739511, 2016). "The causal role of KRas mutants in human cancers was established three decades ago." (PMID 27894102, 2016). "The occurrence of KRAS activating point mutations is reported being mutually exclusive to EGFR mutations in treatment naïve patients possible due to their overlapping pathways in the onset of cancer." (PMID 27528220, 2016). "Especially notable in the case of KRAS is the near coincidence of the clusters of synonymous mutations at G12, G13, and G60, with the classic missense mutations at G12, G13, and Q61 that drive human cancers." (PMID 27684555, 2016). "Somatic mutations in KRAS gene act as an early event in the carcinogenesis of human cancers." (PMID 27517148, 2016). "Type I cancers commonly exhibit mutations in KRAS, BRAF, CTNNB1, PIK3CA, PTEN, ARID1A, or PPP2R1A." (PMID 27421040, 2016). "Synonymous mutations in the KRAS gene are clustered at G12, G13, and G60 in human cancers." (PMID 27684555, 2016). "These transformed phenotypes suggest that synonymous mutations found in driver genes such as KRAS may play a role in human cancers." (PMID 27684555, 2016). "In summary, our data supported the hypothesis that p21 activation could serve as a synthetic lethal factor in KRAS-mutant cancer cells and that p21 itself may be a novel therapeutic target for cancers with KRAS mutations." (PMID 27193833, 2016). "We realized that additional gene mutations may coexist with KRAS or EGFR mutations in cancer cells and may also affect the function of ZEB1." (PMID 27456471, 2016). "Previous evidence suggests that KRAS A146T mutations may have oncogenic potential in other cancer types." (PMID 26980732, 2016). "As a result of p21 induction, mitotic stress was augmented in KRAS-mutant cancers, and this stress may cause the observed susceptibility to apoptosis in KRAS-mutant cancers." (PMID 27193833, 2016). "KRAS, an oncogene, is one of the most commonly mutated genes in many cancers." (PMID 27880931, 2016). "Furthermore, in all test samples we correctly obtained the expected KRAS mutation variant defined by the used cancer cell line." (PMID 27064574, 2016). "The differences in KRAS substitution subtypes in different cancers might be entirely explained by differences in mutation patterns between the cancer types." (PMID 26902163, 2016). "Recently, it has been suggested that mutated KRAS clones may emerge in patients during cetuximab treatment over time, thus providing a rationale to understand cancer cell resistance to cetuximab." (PMID 27708224, 2016). "As less doubling time implies faster proliferation rate, the mutation of APC or KRAS may lead to enhanced malignancy of cancers." (PMID 26937901, 2016). "In addition, a subset of the cell lines has mutations in genes that were previously linked to a cancer phenotype, including KRAS (in MDA-MB-231, MIA PaCa-2, Capan-2, AsPC-1, and HCT 116) and CDKN2A (in MCF7, MDA-MB-231, and HCT 116)." (PMID 27630665, 2016). "However, the only gene product in this network that has been explicitly implicated in the movement of cancer cells expressing specifically oncogenic KRas mutants is CDCP1." (PMID 27894102, 2016). "Hence, NF1 loss phenocopies KRAS mutation and patients with such cancers can also be considered a suitable molecular cohort to treat with the selumetinib/docetaxel combination, which has proven benefits in KRAS mutant disease." (PMID 26410619, 2015). "Oncogenic KRas has also been found to cause defects in terminal differentiation of stem or progenitor cells in mouse colon and zebrafish pancreatic cancer models, so it is possible that GFAP expression was lost early during oncogenic KRAS-driven brain tumorigenesis." (PMID 25644510, 2015).
cancer (continued). "Mutation in KRAS gene is one of the most common oncogenic changes in various types of human cancer." (PMID 25685149, 2015). "Thus, the transition of DNA harbouring the epigenetic alteration into the circulation in early stage cancers is seemingly more consistent than the transition of DNA harbouring a KRAS mutation." (PMID 25946211, 2015). "Thus, targeting KRAS mutated proteins or KRAS effectors requires therapeutic agents tailored for both a specific mutated KRAS and cancer tissue." (PMID 25853628, 2015). "The effect of the C118S mutation on the ability of wild-type KRAS to promote HRAS oncogenesis may nevertheless be dependent upon the stage of tumorigenesis or types of cancer." (PMID 25902334, 2015). "Given that wild-type Ras proteins can be activated downstream of oncogenic Kras, yet give rise to opposite effects on tumorigenesis depending on the context, it is important to ascertain their role in the cancer most frequently associated with KRAS mutations, namely pancreatic." (PMID 26452271, 2015). "Activating mutations in the KRAS gene are highly prevalent in colorectal and other cancers." (PMID 26033452, 2015). "KRAS mutation also is reported to be predictive for poor prognosis and low survival rate in cancer." (PMID 26168967, 2015). "This suggests that inhibition of KRAS or autophagy may sensitize CRC cells harboring KRAS mutations to cancer therapies, reinforcing KRAS-induced autophagy inhibition as an emerging target for CRC therapeutic approaches." (PMID 26418750, 2015). "Serglycin is secreted in elevated levels in cancer cells mutated in KRAS or HER1/EGFR, the fact that may suggest an implication of EGFR-RAS pathway in the biosynthesis and more importantly in secretion of serglycin." (PMID 26581653, 2015). "For this purpose, we established two original cell models for a controlled genetic background where the only difference is the KRAS variant they express: non-cancer colon cells derived from normal human colon mucosal epithelium (NCM460) and a “humanized” Saccharomyces cerevisiae." (PMID 26418750, 2015). "Moreover, alternate pathways through mutation in BRAF and KRAS genes are associated with the progression of polyps to cancer." (PMID 25932044, 2015). "In PDAC cancer cells are addicted to expression of the mutated KRAS." (PMID 26009994, 2015). "Kirsten rat sarcoma viral oncogene homolog (KRAS) is one the most frequent molecular drivers in human cancers and activating mutations of the KRAS gene have been found in a wide variety of tumors with greater frequencies in pancreas, colorectal and non-small cell lung cancer (NSCLC)." (PMID 26468985, 2015). "Interestingly, next-generation sequencing of eight SDH-negative GIST cases using a targeted cancer-associated gene capture library identified a low-frequency (8 %) frameshift NF1 mutation in a GIST that also harbored an activating KRAS gene mutation (G12V)." (PMID 26555092, 2015). "KRAS is one of the most frequently mutated oncogenes in human cancer, yet remaining undruggable." (PMID 25853628, 2015). "In addition, compared with KRAS-wild type carcinomas, KRAS-mutated carcinomas were more likely located in proximal colon (28.3% vs 18.7%, P = 0.004)." (PMID 25929517, 2015). "However, activating mutations, which frequently occur in many types of cancer, turn KRAS into one of the most prominent oncogenes." (PMID 24368337, 2014). "Significant family history of cancer in KRAS-mutated NSCLC in our study implies that smoking habits may be inherited in families of these patients." (PMID 25158139, 2014). "Therefore, the efficient, accurate, and fast analysis for detecting KRAS mutations status in cancer patients before selecting such type of targeted therapy is considered quite important." (PMID 24884535, 2014).
cancer (continued). "The hierarchical tree of this subset of probes revealed two distinct clusters: Group 1, mostly composed by TAs and MSS cancers with KRAS mutations; and Group 2 with BRAF mutations, which consisted of cancers with MSI and MLH1 methylation (Group 2A), and SSAs without MLH1 methylation (Group 2B)." (PMID 24964857, 2014). "In addition, the KRAS-variant appears to predict cancer biology in all cancers thus far studied, including those for which it does not appear to predict increased risk." (PMID 24732316, 2014). "The let-7 miRNA is complementary to the KRAS 3′UTR polymorphism as a possible risk factor for cancer and the let-7 family may be involved in KRAS gene regulation." (PMID 24932237, 2014). "For example, many studies are examining the potential of the KRAS-variant as a cancer biomarker." (PMID 25433809, 2014). "An open question is whether different KRAS mutations at codon-12 affect cellular metabolism differently with possible implications for different responses to cancer treatments." (PMID 24952473, 2014). "Interestingly, KRAS mutations and amplifications are largely mutually exclusive in these cancer types." (PMID 24874471, 2014). "Therefore, we retrospectively reviewed data from patients with advanced cancer and KRAS mutations who were treated in the Phase I Clinical Trials Program at The University of Texas MD Anderson Cancer Center." (PMID 25313136, 2014). "Nevertheless, human mutated gene sequences (e.g., KRAS) associated with the primary human cancers were transferred to the transformed murine fibroblasts by plasma DNA taken from human cancer patients, which then proved to be malignant in genetically-compatible mice." (PMID 25259521, 2014). "In addition, the clinical potential of sequence variants in the 3′ UTR of KRAS as a cancer biomarker by altering the function of miRNAs is discussed." (PMID 25433809, 2014). "KRAS gene mutations were detected in the cancer tissue of 24 out of 56 cases studied (42.85%)." (PMID 25412182, 2014). "KRAS gene mutations were detected in the cancer tissue of 24 cases (42.85%)." (PMID 25412182, 2014). "The differences observed in the incidence of CRC according to different Brazilian regions could relate to the idea that differences in patients origins might contribute to the incidence of somatic mutations in candidate cancer genes such as KRAS." (PMID 24720724, 2014). "Of the 14 carcinomas, 13 were KRAS wild type and one was mutated." (PMID 24454858, 2014). "The relationship between borderline ovarian tumors and low-grade carcinomas has been investigated at the gene level by many groups focusing on the mutually exclusive mutations detected in either the BRAF or KRAS gene, and a relationship was found between the two groups of tumors." (PMID 24886194, 2014). "KRAS mutation is one of the most common oncogenic mutations in human cancers, including PC." (PMID 24194913, 2013). "Activating mutations of KRAS is the most common oncogenic alteration in various human cancers." (PMID 23355875, 2013). "Herein, we report the development of a novel, general and highly sensitive approach for specific, label-free detection of SNPs using the KRAS somatic mutations (codons 12/13) that are widely found in several human cancers (e.g. colorectal, pancreas, ductal and lung) as the model cancer DNA targets." (PMID 23636707, 2013). "Examples are frequent somatic mutations of KRAS codons 12 and 13 in various types of cancers in endodermal organs (pancreas, colon, lung, etc.), and the prevalent mutation in the kinase domain of BRAF, BRAFV600E in cancer cells of endodermal (thyroid, colon) and ectodermal (melanoma) tissues." (PMID 23505473, 2013).